PAX6 (paired box 6)
Diseases named in the same sentence as PAX6 in open-access papers (continued):
Sharing a sentence is not in itself a finding about the gene and the disease.
microphthalmia (64 papers, 2006 to 2025). Congenital or developmental anomaly in which the eyeballs are abnormally small. "Mutations or deletions of the Pax6 gene are linked to congenital eye malformations and neurological developmental abnormalities, such as anophthalmia, microphthalmia, iris defects, iridohypoplasia, and brain/retina retino-cortical dysplasia." (PMID 40806224, 2025). "Pax6 upregulation has been linked to microphthalmia, which aligns with our findings in βA3ΔG91 mice." (PMID 40622998, 2025). "By contrast, missense variants in the paired domain of PAX6 often produce other ocular pathologies, such as microphthalmia, anophthalmia, coloboma, and isolated foveal hypoplasia." (PMID 38849565, 2024). "Deletion of a single copy of pax6 in mice showed microphthalmia, while mutation with a double copy showed anophthalmia." (PMID 37240129, 2023). "Currently, 19 pathogenic variants of PAX6 have been reported to be associated with microphthalmia, most of which are missense variants." (PMID 36816037, 2023). "Microphthalmia and Peters anomaly are associated with several PAX6 mutations, most of which are missense, while anophthalmia is associated with homozygous PAX6 variants." (PMID 36582291, 2022). "A heterozygous, likely pathogenic, variant in PAX6 associated with microphthalmia was reported to have a highly conserved valine residue in the homeodomain." (PMID 32111086, 2020). "Optic nerve coloboma are generally associated with microphthalmia, with missense mutations affecting all of the functional domains of PAX6." (PMID 31861090, 2019). "Mosaicism has been reported in PAX6-associated microphthalmia, such as a case with two brothers with bilateral complex microphthalmia with a heterozygous missense mutation, and an unaffected mosaic mother." (PMID 31416264, 2019). "Accordingly, a recent report has linked novel missense mutations in PAX6 (c.160A>C, p.Ser54Arg and c.372C>A, p.Asn124Lys) to severe bilateral microphthalmia, with phenotype resembling SOX2-associated MAC." (PMID 31861090, 2019). "For example, mutations in PAX6 lead to microphthalmia in most patients but can also cause high myopia associated with axial elongation." (PMID 30689892, 2019). "Of the 13 different mutations that are associated with microphthalmia in the PAX6 Mutation Database, the vast majority are missense, although PTC-inducing mutations have been reported (two nonsense and two frameshifts)." (PMID 31861090, 2019). "Despite the rarity of PAX6-associated microphthalmia, with fewer than 10 variants described to date, it is worth noting that disease recurrence has putatively been associated with mosaicism in a healthy progenitor in two additional families." (PMID 30386378, 2018). "Consistently, the Sey allele produced microphthalmia, decreased corneal epithelial thickness, reduced ocular Pax6 mRNA levels, and reduced PAX6 protein levels." (PMID 30258099, 2018). "Similar missense mutations in the paired-domain of PAX6 have been occasionally reported to cause microphthalmia; thus, this variant seemed to be the cause of the phenotype in the family." (PMID 30386378, 2018). "We also describe a new PAX6 missense variant in an autosomal‐dominant pedigree affected by mild bilateral microphthalmia showing high intrafamiliar variability, with germline mosaicism determined to be the most plausible molecular cause of the disease." (PMID 29178648, 2017). "Among them including Sox2, Otx2, Pax6, have been associated with anophthalmia and microphthalmia in many individuals." (PMID 27494603, 2016). "In mice, disruption of Trpm3 results in a mild pupilary phenotype, whereas, Pax6-deficiency results in a severe eye phenotype characterized by aphakia, microphthalmia and anophthalmia." (PMID 25090642, 2014). "It causes asymmetrical microphthalmia to develop by increasing ROS production and perturbs Pax6 expression." (PMID 24636305, 2014).
microphthalmia (continued). "Previous findings show that heterozygous Pax6 loss of function mutations lead to microphthalmia in mice, which is primarily due to defects in early eye morphogenesis." (PMID 19686589, 2009). "Our results indicate that although both over- and under-expression of Pax6 cause microphthalmia, the underlying mechanisms are different." (PMID 18507827, 2008). "Further sequence analysis of other genes associated with anophthalmia and microphthalmia such as PAX6, BCOR, OTX2, SIX6, and CHD7 is ongoing in this study cohort to determine mutation associations." (PMID 18385794, 2008). "This sequence is different to that underlying microphthalmia in Pax6+/- heterozygotes, which is due primarily to defects in the initial stages of lens formation." (PMID 18507827, 2008). "Heterozygous Pax6+/- embryos show microphthalmia that is thought to be caused by delayed development of the lens and anterior eye structures." (PMID 18507827, 2008). "One clear conclusion from these findings is that while both over- and under-expression of Pax6 cause microphthalmia, the underlying mechanisms are different." (PMID 18507827, 2008). "Mice homozygous for null mutations in the Pax6 gene fail to form eyes whereas mice heterozygous for Pax6 mutations exhibit microphthalmia and have hypoplastic irises and multiple anterior segment defects." (PMID 17029624, 2006). "PAX6 pathogenic variants not only cause defects in ocular tissues, such as the iris and retina, but also lead to maldevelopment of the whole eye, resulting in microphthalmia." (PMID 36816037, 2023). "Moreover, it points to the fact that microphthalmia in Tmem107−/− animals is likely caused by down-regulated Pax6, whereas anophthalmia is rather caused by altered expression of Sox2." (PMID 37863656, 2023). "Microphthalmia/anophthalmia/coloboma phenotypes are significantly associated with recurrent heterozygous PAX6 missense mutations in the paired domain that are likely to disrupt the PAX6–DNA interaction." (PMID 32111086, 2020). "Another limitation is that only 3 causes of foveal hypoplasia were represented within this cohort; the grading system was not applied to other conditions associated with foveal hypoplasia such as PAX-6 mutation, retinopathy of prematurity, nanophthalmos, and other photoreceptor dystrophies." (PMID 31937464, 2020). "However, Kim and Lauderdale showed that Pax6ΔPD has a distinct function in mammalian eye development than Pax6 and Pax6(5a), since the overexpression of Pax6ΔPD, while using BAC and YAC transgene systems, lead to severe microphthalmia in both wildtype and Pax6-deficient mice." (PMID 31861090, 2019). "By contrast, missense mutations usually exhibit a moderate impact on PAX6 functionality and are often associated with some atypical PAX6-associated phenotypes, such as mild forms of iris coloboma or isolated foveal hypoplasia, or more severe phenotypes of Peter’s anomaly and microphthalmia." (PMID 30386378, 2018). "Previous research has linked mutations in genes such as CHX10, MAF, PAX6, PAX2, RX (RAX), SHH, SIX3, OTX2, and SOX2 to phenotypes associated with microphthalmia, anophthalmia, and coloboma (MAC)." (PMID 39129019, 2024). "Previous studies found that in mice and Xenopus, the overexpression of pax6 leads to several eye defects, including microphthalmia, ectopic eyes, and anophthalmia." (PMID 36007075, 2022). "The previously published variant c.372C>A, p.(Asn124Lys) resulted in severe disruption of the PAX6 DNA-binding activity during early eye formation, giving rise to a left microphthalmia and right optic nerve coloboma." (PMID 34101622, 2021). "Lens-specific Lss knockout mice generated using Pax6-cre showed microphthalmia and small cloudy lenses." (PMID 34926465, 2021). "Similar phenotypes of congenital aphakia, microphthalmia, and anterior segment dysgenesis have been only reported for some FOXE3 and PAX6 mutations, two transcription factors involved in lens vesicle formation." (PMID 32791987, 2020).
microphthalmia (continued). "As already noted, Pax6−/− null homozygotes are anophthalmic and die around birth and heterozygotes have significant ocular defects including microphthalmia." (PMID 27240603, 2016). "This accords with a comparable model for Shh's effect on reactive astrocytes, and is a well-recognized feature of transcription factors, as exemplified by the effects of altered Pax6 dosage in inducing microphthalmia." (PMID 25010521, 2014). "As major causative genes for simple microphthalmia, CHX10 (Ceh10 homeodomain gene; OMIM 142993), PAX6 (Paired box gene 6; OMIM 607108), and MFRP (Membrane-type frizzled-related protein; OMIM 606227) probably induce the failure of ocular differentiation." (PMID 19452014, 2009). "As expected with genes expressed in the developing brain, patients with inherited PAX6 and SOX2 mutations exhibit CNS malformations in addition to dominantly inherited anophthalmia/microphthalmia." (PMID 18039390, 2007). "Abnormal expression of Pax6 could lead to abnormal eye development, resulting in microphthalmia microphthalmos in mice and anophthalmia anophthalmos in fruit flies." (PMID 40806224, 2025). "PAX6 and SOX2 are transcription factors associated with anophthalmia and microphthalmia in humans." (PMID 37863656, 2023). "Coloboma and microphthalmia in index patient 6[II:1] could result from PAX6 downregulation due to reduced levels of BRPF1 protein, as haploinsufficiency of PAX6 is associated with C/M." (PMID 33418956, 2021). "This regulation of Pax6 by Cse1l may explain the early onset cataracts and microphthalmia in Cse1lnull/wt mice, as well as the range of eye abnormalities in the anteater mutants." (PMID 34287339, 2021). "As microphthalmia is very rarely reported in aniridia, and in some cases is thought to be caused by mutations in other important eye genes such as SOX2 and OTX2 in addition to the aniridia causing PAX6 mutation." (PMID 30258099, 2018). "This recovery was most distinguishable as Pax6 prevented the occurrence of microphthalmos." (PMID 26744353, 2016). "For example, Meis homeobox 2 (MEIS2) modulates PAX6 transcription activity, and in madaka fish morpholino-mediated ablation of miR-204 targeting Meis2 results in an eye phenotype characterized by microphthalmia, abnormal lens formation, and altered dorsoventral patterning of the retina." (PMID 22550392, 2012). "Conversely, increasing dosages of the Pax6 gene also lead to microphthalmia and malformed retinas." (PMID 19686589, 2009). "Kondoh and colleagues have shown that PAX6 and SOX2 co-bind to a regulatory element driving lens induction in the chick, which suggests that lens induction failure could be responsible for microphthalmia in patients with mutations in these genes." (PMID 18039390, 2007). "Furthermore, we show that overexpression of a short PAX6 isoform derived from an internal promoter in a multicopy YAC transgenic line results in a microphthalmia phenotype." (PMID 17014839, 2006). "It is worth noting that many large deletions, even the whole PAX6 deletion, are not found to be associated with microphthalmia, and on the contrary, some missense mutations could lead to microphthalmia." (PMID 36816037, 2023). "The types of eye abnormalities (microphthalmia plus cataracts) reported in abstract form for Le-CreTg/Tg homozygotes on a mixed genetic background are also consistent with an effect that is mediated via altered Pax6 levels but less penetrant on FVB than some other genetic backgrounds." (PMID 25272013, 2014). "The fact that major retinal defects appear after RGC defects in axon guidance and Shh expression supports the hypothesis that microphthalmia and retinal dysplasia in PAX77+/+ eyes could be secondary to earlier abnormalities in RGC differentiation caused by Pax6 overexpression." (PMID 18507827, 2008).
microphthalmia (continued). "The developmental events that lead to microphthalmia in PAX77 mice are not well-characterised, so it is not clear whether over- and under-expression of Pax6/PAX6 cause microphthalmia through similar mechanisms." (PMID 18507827, 2008). "As the microphthalmia phenotype is observed in 3 independent multicopy lines (2 BAC and 1 YAC) it is unlikely to be caused by disruption of a gene at the transgene insertion site, but most likely to be the result of the overexpression of a paired-less PAX6/Pax6 isoform." (PMID 17014839, 2006). "We analyzed the expression of PAX6, PAX2, and SOX1 in microphthalmia mutants because structures expressing these proteins are missing in animals with anophthalmia, which we also see in our mutants." (PMID 37863656, 2023). "Mutations in the same gene resulting in both high myopia and microphthalmia have been observed for a few other genes like FZD5 and PAX6, suggesting bidirectional roles of these genes in early ocular development." (PMID 34926457, 2021). "Overexpression of Pax6 in PAX77+/+ mice prevents normal development of the retina from about E14.5 and results in microphthalmia, retinal dysplasia, and defective retinal ganglion cell axon guidance in postnatal life." (PMID 32111086, 2020). "However, Pax6 plasmid microinjection could prevent the occurrence of microphthalmos." (PMID 26744353, 2016). "Moreover, the reduction of SOX1 expression was found in the lens of microphthalmia mutants, whereas PAX2 and PAX6 were down-regulated in the distal part of NR." (PMID 37863656, 2023). "Clinical sequencing and deletion/duplication analysis of PAX6, FOXC1, PITX2, and CYP1B1, as well as a clinical microphthalmia/anophthalmia gene panel, did not reveal causative variants." (PMID 33973683, 2021). "Thus, the possibility of PAX6 mosaicism should also be considered when explaining occurrence in two or more affected siblings with microphthalmia in the absence of family history." (PMID 30386378, 2018). "Overexpression of Pax6 in the mouse eye can also affect the normal development of anterior segment, resulting in similar eye phenotypes to KTA048 mutants, including corneal opacity, iris hypoplasia, abnormal lens fiber cell differentiation, microphthalmia and retinal dysplasia." (PMID 24895407, 2014).
cataract (41 papers, 2005 to 2026). Partial or complete opacity of the crystalline lens of one or both eyes that decreases visual acuity and eventually results in blindness. "Patient #1 had a deletion on chromosome 11, including PAX6, which is a gene well-known to be associated with cataracts and other types of anterior segment dysgenesis." (PMID 36980880, 2023). "We then focused on two highly expressed proteins in the lens with an important number of putative SQ/TQ sites and whose mutation causes the development of cataracts: Pax6 (3 SQ/2 TQ) and FYCO1 (10 SQ/6 TQ)." (PMID 37626928, 2023). "Some of the congenital cataracts stem from mutations of transcription factors such as Pax6, Pitx3, Eya and others." (PMID 19936087, 2007). "Natural history of cataracts in patients with PAX6 mutations." (PMID 34101622, 2021). "In general, the mutation in PAX6 disturbs the entire downstream signaling cascade, leading to a spectrum of ocular phenotypes, as evidently documented in the literature, in several families with unusual phenotypes, along with cataracts." (PMID 33339270, 2020). "In addition to FH, PAX6 mutations can be associated with keratopathy, cataracts, glaucoma and optic nerve hypoplasia thus resulting in much more reduced vision compared with SLC38A8 mutations and albinism." (PMID 32744312, 2020). "Similarly, overexpression of Pax6 in the mouse also causes cataracts, with partial failure of lens fibre differentiation and abnormalities in fibre shape as well as fibre cell/lens capsule and fibre cell/fibre cell interactions." (PMID 18939978, 2008). "More recently, we found that during cataractogenesis, Pax6 SUMOylation is much enhanced in cataract patients." (PMID 37683133, 2023). "In this retrospective review, the co-occurrence of cataracts with PA that has been reported in most affected cases clearly indicates that Pax6 is required for proper gene expression in the human lens." (PMID 35029171, 2022). "We recently analyzed the expression patterns of both sumoylation ligases and desumoylation enzymes and their target, Pax6 in different groups of cataract patients." (PMID 34226295, 2021). "It was reported that the severity of iris hypoplasia varied in different PAX6 cases and lens abnormalities include various degrees and types of cataracts and lens ectopic." (PMID 34016071, 2021). "After comparative analysis of the p46 and p32 Pax6 in senile cataractous lenses of different age groups, we next examined the relative expression levels and sumoylation patterns of both p46 and p32 Pax6 in cataract patients with other complications." (PMID 32827359, 2020). "Among different cataract patients from 50s to 70s, male patients express more sumoylation enzymes and p46 Pax6." (PMID 32827359, 2020). "In the present studies through analysis of the changes of the non‐sumoylated and sumoylated p32 Pax6 in different groups of cataract patients, we clearly demonstrated that the non‐sumoylated p32 Pax6 is increased in those from 50s to 60s." (PMID 32827359, 2020). "The presence of strong p46 Pax6 expression in capsular epithelia of cataract patients of different age groups prompts us to explore its possible functions in the adult lenses." (PMID 32827359, 2020). "It is also a differentially expressed protein in the development of cataracts, and is a major target of the Pax6 pathway during lens development." (PMID 32393163, 2020). "Analysis of the pooled epithelial cell samples from complicated cataract patients of 50s to 90s revealed the presence of di‐sumoylated p46 Pax6." (PMID 32827359, 2020). "The p46 Pax6 displays age‐dependent decrease in normal lens, remains relatively stable in senile cataracts but becomes di‐sumoylated in complicated cataracts." (PMID 32827359, 2020). "Conversely, overexpression of Pax6(5a) in the mouse lens leads to the formation of cataracts and up-regulation of a number of cellular adhesion molecules, while Pax6(5a) overexpression in the chick retina induces hyperplasia of the neural retina." (PMID 16725027, 2006).
cataract (continued). "Both P32 Pax6 and P46 Pax6 are SUMOylated in cataract patients." (PMID 37683133, 2023). "In contrast, di‐sumoylated p46 Pax6 can be used as a molecular marker for complicated cataracts." (PMID 32827359, 2020). "Although the role of the four studied genes: PAX6, PITX3, HSF4 and LIM2 in both ocular and central nervous system development, we report the absence of mutations in all studied genes in four families with phenotypes associating cataract, MR and microcephaly." (PMID 22103961, 2011). "Also, over-expression of Pax6 expression in the mouse lens results in augmented levels of α5β1-integrin and subsequent early, postnatal cataracts." (PMID 19936087, 2007). "Moreover, male cataract patients displayed a higher level of Pax6 than female patients did." (PMID 32827359, 2020). "Since we have previously demonstrated that SUMO1 conjugation of Pax6 is necessary to activate its functions during lens development, we next sought to determine whether the Pax6 level and sumoylation status display dynamic changes in cataract patients of different age groups." (PMID 32827359, 2020). "Moreover, common mutations associated with cataracts of various morphologies include genes encoding crystallins (CRYA, CRYB, and CRYG), lens specific connexins (Cx43, Cx46, and Cx50), major intrinsic protein (MIP) or aquaporin, heat shock transcription factor 4 (HSF4), etc. but PAX6 is neglected." (PMID 36843716, 2023).